RNU6-33P (RNA, U6 small nuclear 33, pseudogene)
Synonyms: RNU6-33
Gene: Small nuclear RNA gene on chromosome 4 (88,684,848 to 88,684,954, reverse strand). Ensembl gene ENSG00000207524.
Homologues: Orthologues: dog U6 (100% identical), rat LOC120101146 (100% identical), rat U6 (100% identical), rat U6 (99% identical). Paralogues in human: RNU6-1 (99% identical), RNU6-2 (99% identical), RNU6-3P (99% identical), RNU6-4P (99% identical), RNU6-5P (99% identical), RNU6-6P (99% identical), RNU6-9 (99% identical), RNU6-12P (98% identical), RNU6-13P (98% identical), RNU6-17P (98% identical), RNU6-18P (98% identical), RNU6-25P (98% identical), and 1287 more.